CTNNB1 (catenin beta 1)
Diseases named in the same sentence as CTNNB1 in open-access papers (continued):
Sharing a sentence is not in itself a finding about the gene and the disease.
pancreatic cancer (42 papers, 2014 to 2025). "In addition, CTNNB1 mutations are the only actionable genomic lesions in solid pseudopapillary neoplasms relative to other common subtypes of pancreatic tumors." (PMID 34488905, 2021). "Furthermore, of the 328 pancreatic tumors included in the cBioPortal database only 12 (3.7%) harbored CTNNB1 exon 3 mutations." (PMID 30972907, 2019). "Furthermore, TCGA data portal shows that human PDACs exhibit amplifications and mutations in ADAM10, MYC, VIM (vimentin), CD44, CCND1 (CyclinD1) and CTNNB1 (β-catenin), implying the importance of interfering with the signaling associated with these in prevention of pancreatic cancer." (PMID 26440150, 2015). "TSPAN1 is also overexpressed in pancreatic cancer via family members with sequence similarity 83 (FAM83A) in the canonical WNT-Catenin Beta 1 (CTNNB1) signaling pathway." (PMID 38559560, 2024). "Predicted to be targeted by miR409, Catenin Delta 1 (CTNND1) along with Catenin alpha 1 (CTNNA1) and Catenin Beta 1 (CTNNB1) expression was shown to indicate a poor prognosis for pancreatic cancer patients." (PMID 36983764, 2023). "In many more cases, a gene that shows high selectivity is selectively essential within each lineage (e.g., only partial dependence on CTNNB1 in liver, lung, and pancreatic cancers, or on IRF4 in skin cancer)." (PMID 33554860, 2021). "Most sites from which tumors are most likely to metastasize—colorectal, esophageal, lung, ovarian, and pancreatic cancer—had low prevalences of both CDH1 and CTNNB1 mutations." (PMID 29156750, 2017). "Moreover, the CTNNB1 gene is rarely mutated in pancreatic cancer irrespective of the histologic type." (PMID 35913675, 2023). "LncRNA TSLNC8 promotes the binding of RNA-binding protein HuR with CTNNB1 mRNA and increased the stability of CTNNB1 mRNA, thus activating WNT/β-catenin signaling pathway in pancreatic cancer." (PMID 36973749, 2023). "CTNNA1, CTNNB1, and CTNND1 are key molecules potentially involved in pancreatic cancer metastasis mediated by hsa-miR-30d-5p/GJA1." (PMID 36741258, 2023). "AKT1, CDKN2A, ERBB2, and IL6 are common protein core of liver and pancreatic cancers, while STAT3, CASP3, NOTCH1, and CTNNB1 are possible differential proteins to discriminate these cancers." (PMID 35154607, 2021). "The current results indicate that AKT1, CDKN2A, ERBB2, and IL6 are the common protein core of liver and pancreatic cancers, and STAT3, CASP3, NOTCH1, and CTNNB1 are possible differential proteins that discriminate these cancers." (PMID 35154607, 2021). "It has been recently reported that the disruption of nuclear complexes of CTNNB1 and HNF1A suppressed pancreatic tumor growth." (PMID 29515771, 2018). "Moreover, survival analysis shows that pancreatic cancer patients with high expression of CTNNA1, CTNNB1, or CTNND1 have a poor prognosis." (PMID 36741258, 2023). "Additionally, CTNNB1 had the highest deep deletion rate across pan-cancer at 5%, followed by TGFB1 at 3.6% in head and neck cancer and 2.2% in non-small cell lung cancer, and TNF and PPARG in pancreatic cancer with rates of 3.6% and 1.3%, respectively." (PMID 37033970, 2023).
pancreatic cancer (continued). "Although there are scientific reports on the prognostic values of SMAD3 and CTNNB1 in pancreatic cancer, the precise functions of Jun Oncogene (JUN) and TCF-7 in the pathogenesis of pancreatic cancer are still largely unknown and require further understanding and research." (PMID 33194391, 2020).
lung adenocarcinoma (30 papers, 2014 to 2025). A carcinoma that arises from the lung and is characterized by the presence of malignant glandular epithelial cells. "Mutations in the gene encoding β-catenin, CTNNB1 mutations, were related to recurrence of early-stage lung adenocarcinoma in our study." (PMID 33140254, 2021). "Relapse caused by CTNNB1 mutation or fusion genes accounted for approximately 30% of all recurrence cases of stage I lung adenocarcinoma." (PMID 33140254, 2021). "It has been reported that CTNNB1 mutation was highly associated with many kinds of human tumors, such as biliary tract cancer, lung adenocarcinoma, and endometrioid ovarian carcinoma." (PMID 32596147, 2020). "CTNNB1 has been found to be genetically mutated in various human cancers, including lung adenocarcinoma, whose gene expression was increased in lung tissue with pulmonary fibrosis." (PMID 32457348, 2020). "During follow-up, 19 (63.3%) patients with lung adenocarcinomas with mutated CTNNB1 and 259 (48.5%) patients with lung adenocarcinomas with wild-type CTNNB1 experienced a relapse, and 10 (33.3%) and 111 (20.8%) patients died, respectively." (PMID 32117418, 2019). "In this study, we describe the clinicopathological characteristics of lung adenocarcinoma with CTNNB1 mutation." (PMID 32117418, 2019). "Lung adenocarcinoma with CTNNB1 mutation is relatively uncommon, and its clinicopathologic characteristics, disease course, and prognosis have not been well-studied." (PMID 32117418, 2019). "In our study, during follow-up, 19 patients (63.3%) with lung adenocarcinomas with CTNNB1 mutations and 259 patients (48.5%) with lung adenocarcinomas with wild-type CTNNB1 relapsed, and 10 (33.3%) and 111 (20.8%) patients died, respectively." (PMID 32117418, 2019). "They observed the lung adenocarcinoma caused by mutation in CTNNB1 may show post‐operative reoccurrence in patients having mutated EGFR." (PMID 39434198, 2024). "Characteristics of lung adenocarcinoma with CTNNB1 mutation." (PMID 32117418, 2019). "Of the 564 lung adenocarcinoma patients examined, 30 (5.3%) harbored CTNNB1 mutations." (PMID 32117418, 2019). "Features of patients with lung adenocarcinoma harboring CTNNB1 mutations." (PMID 32117418, 2019). "Of 564 lung adenocarcinoma patients, 30 (5.3%) harbored CTNNB1 mutations." (PMID 32117418, 2019). "Therefore, we compared the clinicopathologic characteristics of 30 lung adenocarcinomas with CTNNB1 mutations with those of 534 lung adenocarcinomas with wild-type CTNNB1." (PMID 32117418, 2019). "Hence, oncogenic CTNNB1 mutations may be found in about 6% of lung adenocarcinomas and may predict post-operative recurrence in EGFR-mutant LUADs." (PMID 37347751, 2023). "When circXPO1 binds to IGF2BP1 and enhances the stability of CTNNB1 mRNA, CTNNB1 inhibition is increased and lung adenocarcinoma progression is promoted." (PMID 34445958, 2021). "To validate this axis in clinical samples, we downloaded and analyzed the gene expression profiles of HIF1A, CASC15, SOX4, and CTNNB1 (β-catenin) in two lung adenocarcinoma cohorts from TCGA database." (PMID 33407675, 2021). "The lung adenocarcinoma dataset SRA ERP001058 contains 41 tumors with known targetable or oncogenic mutations in 6 genes: EGFR, KRAS, NRAS, MET, BRAF and CTNNB1." (PMID 30255803, 2018). "Our data provide evidence that S100A15 aggravates metastatic progressing in lung adenocarcinoma in vivo and in vitro through DNA hypomethylation over its gene promoter region, and CTNNB1-centered down-stream mediators." (PMID 28498804, 2017). "Increased S100A15 expression and decreased DNA methylation of its gene promoter region were associated with high metastasis potential and poor outcome in lung adenocarcinoma, probably through triggering CTNNB1 -centered pathways." (PMID 28498804, 2017).
lung adenocarcinoma (continued). "A finding in this NGS study was that CTNNB1 mutations or fusion genes were independent negative prognostic factors for recurrence in early-stage lung adenocarcinoma." (PMID 33140254, 2021). "Although CTNNB1 mutation occurs in many tumors types, it has not been well-studied in the context of lung adenocarcinoma, and the clinicopathologic characteristics and prognosis of lung adenocarcinoma with mutated CTNNB1 has not been described." (PMID 32117418, 2019). "Female patients and nonsmokers are likely to harbor CTNNB1 mutation and primary lung adenocarcinoma with mutated CTNNB1 has a poor prognosis." (PMID 32117418, 2019). "In summary, our results suggest that female patients and nonsmokers are likely to harbor CTNNB1 mutation and primary lung adenocarcinoma with mutated CTNNB1 has a poor prognosis." (PMID 32117418, 2019). "Overall, our data reveal an important physiological role for S100-A15 in comprehending the proliferative, metastatic, and invasive properties of lung adenocarcinoma which may be orchestrated by CTNNB1 with the involvement of ZEB1, CDC42, HSP90AA1, PCNA and BST2." (PMID 28498804, 2017). "A cohort of 293 lung adenocarcinoma (LUAD) patients was categorized into two groups, the high-CTNNB1 and low-CTNNB1 groups, based on the expression level." (PMID 37881428, 2023). "Based on the TCGA data, we constructed a lung adenocarcinoma prognosis model, and we found five key Wnt signaling pathway related genes, including AXIN1, CTNNB1, LEF1, FZD2, FZD4." (PMID 36703749, 2022). "Examples were NSD1 in HNSC, CTNNB1 in liver hepatocellular carcinoma (LIHC), and STK11 and KEAP1 in lung adenocarcinoma (LUAD)." (PMID 29125844, 2017). "Three genes, PTCH1, CTNNB1, and FYN, have been predicted to contribute to the initiation and progression of lung adenocarcinoma in all the six gene sets." (PMID 27412431, 2016). "Notably, a previous study revealed that circXPO1 binds with IGF2BP1 to raise catenin beta 1 (CTNNB1) mRNA stability, thereby promoting lung adenocarcinoma progression." (PMID 37370759, 2023). "In multivariate analysis adjusted for age, sex, smoking history, stage, surgical mode, and visceral pleural invasion, the CTNNB1 mutation and fusion genes (ALK, ROS1, RET) were negative prognostic factors for recurrence in early-stage lung adenocarcinoma (HR 4.47, p = 0.001; HR 2.73, p = 0.009)." (PMID 33140254, 2021).
glioma (27 papers, 2013 to 2025). A benign or malignant brain and spinal cord tumor that arises from glial cells (astrocytes, oligodendrocytes, ependymal cells). "Similarly, in patients with high grade and poor prognosis glioma, DJ-1 expression has been associated with a higher level of protein catenin beta 1 (CTNNB1)." (PMID 35563738, 2022). "CTNNB1, the mRNA which encoded β-catenin, was up-regulated in tissues and cells of glioma." (PMID 32009853, 2020). "The results obtained for the CTNNB1 gene show that the changes were most frequently confined to grade 3 gliomas." (PMID 40679044, 2025). "We identified linear associations between the expression of the DKK3, CTNNB1, FSTL1, and CSNK1A1 genes classified by the WHO glioma grade." (PMID 37149563, 2023). "On the other hand, circ_0055412 sequestered miR‐330‐3p and regulated NFATC3 expression to promote the transcription of CTNNB1, which enhanced β‐catenin and activated Wnt/β‐catenin pathway, thereby improving the cisplatin resistance of glioma cells." (PMID 35332692, 2022). "For instance, SNHG17, as a sponge of miR-506-3p, was clarified to upregulate the expression of CTNNB1 in glioma." (PMID 34497156, 2021). "Using IM-12 or CTNNB1 plasmid significant reversed the oncogenic function of FTL in mediating EMT in glioma, which strongly indicated that FTL promoted EMT by regulating AKT/GSK3β/ β-catenin signaling." (PMID 32677981, 2020). "The findings that YY1-induced SNHG17 facilitated the glioma progression through targeting miR-506-3p/CTNNB1 axis to activate Wnt/β-catenin signaling pathway offered a brand-new prospects to molecular-targeted treatment for glioma." (PMID 32009853, 2020). "SNHG17 induced by YY1 facilitated the glioma progression through targeting miR-506-3p/CTNNB1 axis to activate Wnt/β-catenin signaling pathway." (PMID 32009853, 2020). "Prior to all, levels of CTNNB1 and its protein β-catenin were effectively up-regulated in glioma cells after the transfection of pcDNA3.1/CTNNB1." (PMID 32009853, 2020). "Rescue experiments illustrated that overexpression of CTNNB1 offset the inhibitory effect resulted from SNHG17 depletion in glioma cells." (PMID 32009853, 2020). "The results proved that SNHG17 induced by YY1 facilitated the glioma progression through targeting miR-506-3p/CTNNB1 axis by activation of Wnt/β-catenin signaling pathway, suggesting its potential value as a biomarker in glioma." (PMID 32009853, 2020). "Rescue experiments indicated that CTNNB1 overexpression abolished the inhibitory effects of SNHG7 inhibition on glioma progression." (PMID 32009853, 2020). "Based on previously published studies and our current findings, we herein present schematic illustrations of the hypothetical role of DKK3 in glioma progression considering its interaction with CTNNB1, FSTL1, and CSNK1A1, which are involved in the Wnt/β-catenin signaling pathway." (PMID 37149563, 2023). "The correlation of ASCL2 and CTNNB1 (β‐catenin) was significant in TCGA gliomas dataset." (PMID 35882624, 2022). "In general, SNHG17 promoted glioma progression through up-regulating CTNNB1 expression." (PMID 32009853, 2020). "Furthermore, we verified that SNHG17 negatively regulated miR-506-3p expression meanwhile miR-506-3p negatively regulated CTNNB1 expression in glioma." (PMID 32009853, 2020). "Via RT-qPCR, up-regulated expression of CTNNB1 was observed in glioma tissues and cell lines." (PMID 32009853, 2020). "RT-qPCR revealed SNHG17, YY1, miR-506-3p, CTNNB1 expression among glioma cells." (PMID 32009853, 2020). "Interestingly, there were Wnt/β-catenin-related genes whose mRNA expression levels were noticeably increased in GBM compared with grade II and III glioma, and those genes were catenin beta 1 (CTNNB1), follistatin-like 1 (FSTL1), and casein kinase 1 alpha 1 (CSNK1A1)." (PMID 37149563, 2023).
glioma (continued). "Additionally, as shown on the example of gold quantum dots (AuQDs), they can suppress metastasis of cancer cells and spheroid cell growth due to the inhibition of CTNNB1 (catenin beta 1) signaling, thus restricting the malignant properties of glioma stem-like cells." (PMID 35884903, 2022). "On the other hand, when the relationships between CSNK1A1 and CTNNB1 and between FSTL1 and CTNNB1 were estimated, positive correlations with similar slopes were shown in both grade II or III glioma and GBM." (PMID 37149563, 2023). "We also observed that as the grade of glioma increased, DKK3 expression showed a tendency to be more strongly positively correlated with the expression of CTNNB1, FSTL1, and CSNK1A1, which are related to the Wnt/β-catenin pathway." (PMID 37149563, 2023). "We calculated the correlations between the expressions levels of the DKK3, CTNNB1, FSTL1, and CSNK1A1 genes and eight immune cell fractions in grade II or III glioma and GBM." (PMID 37149563, 2023). "When determining the relationships among DKK3, FSTL1 and CTNNB1, we observed that the higher the grade of glioma was, the stronger the positive correlations between DKK3 and FSTL1 and between DKK3 and CTNNB1." (PMID 37149563, 2023). "The expressions of SNHG17, miR-506-3p and CTNNB1 in tissues were detected by RT-qPCR, showing that SNHG17 and CTNNB1 expressions were reduced but miR-506-3p expression was increased in glioma tissues with SNHG17 overexpression compared with sh-NC group." (PMID 32009853, 2020). "For signaling pathways genes, the expression of CXCR4, BIRC5, CTNNB1, FZD4, and MET were significantly increased in high-grade gliomas." (PMID 32154177, 2020). "Given that CTNNB1 was the mRNA of β-catenin; we speculated SNHG17 might regulate Wnt/β-catenin signaling pathway via up-regulating the expression of CTNNB1 in glioma." (PMID 32009853, 2020). "To further investigate why SNHG17 activated Wnt/β-catenin signaling pathway in glioma, we hypothesized that SNHG17 might influence CTNNB1 expression to activate Wnt/β-catenin signaling pathway." (PMID 32009853, 2020).